CHGA (chromogranin A)
Diseases named in the same sentence as CHGA in open-access papers (continued):
Sharing a sentence is not in itself a finding about the gene and the disease.
pheochromocytoma (continued). "This case underscores the diagnostic complexity of feline pheochromocytoma and highlights the importance of integrating imaging, histopathology, and immunohistochemistry, as chromogranin A negativity does not exclude this diagnosis." (PMID 42095012, 2026). "While pheochromocytoma is often suspected in the setting of hypertensive crises and elevated catecholamines, clinicians should consider alternative sources in the presence of widespread malignancy and normal chromogranin A levels." (PMID 40666573, 2025). "Chromogranin A is also released by neuroendocrine tissues along with catecholamines; nevertheless, it is a sensitive and specific diagnostic tool in detecting pheochromocytomas (familial and sporadic) rather than paragangliomas." (PMID 34072806, 2021). "Interestingly, the concentration of plasma chromogranin A also predicts the size of the pheochromocytoma." (PMID 35054195, 2021). "Only two patients had high Chromogranin A levels, a marker for pheochromocytoma/paraganglioma." (PMID 34072806, 2021). "In addition to secreting the catecholes dopamine, epinephrine and norepinephrine, numerous other hormones have been isolated from pheochromocytomas including adrenocorticotropin, vasoactive intestinal peptide, neuropeptide Y, IL-6, calcitonin, and chromogranin A." (PMID 21843357, 2011). "After a retroperitoneal ultrasound, he was found to have a 7 cm mass in the right adrenal gland with elevated chromogranin A, urine vanillylmandelic acid (VMA), and urinary 24-hour metanephrines to confirm the diagnosis of a pheochromocytoma." (PMID 34707965, 2021). "Immunohistochemistry revealed synaptophysin positivity with negative chromogranin A staining, supporting a diagnosis of pheochromocytoma." (PMID 42095012, 2026). "Immunohistochemically, the neoplastic cells were strongly positive for chromogranin A but negative for cytokeratin and vimentin, consistent with a diagnosis of pheochromocytoma of medullary origin." (PMID 41227489, 2025). "The negative staining for chromogranin A (CgA) ruled out pheochromocytoma, while the absence of melan-A, inhibin, and calretinin excluded adrenocortical tumors." (PMID 39493270, 2024). "All had normal levels for Chromogranin A (0–85 ng/mL), a tumor marker for pheochromocytomas/paragangliomas, except for patients No. 7 (156.5 ng/mL), 26 (231.4 ng/mL) and 27 (224.7 ng/mL)." (PMID 35054195, 2021). "Even though two of our patients had elevated Chromogranin A levels, all tumors were otherwise biochemically silent and no pheochromocytoma was detected." (PMID 34072806, 2021). "Concerning other laboratory findings: serum calcitonin was elevated in both patients with medullary thyroid cancer, while chromogranin A was elevated in 6 patients: in 4 patients with NET (2 with pulmonary carcinoid and 2 with pancreatic NET) and 1 with pheochromocytoma and 1 with ovarian carcinoma." (PMID 33237923, 2020). "The analysis of two non-neoplastic breast specimens gave negative results, whereas two cases of pheochromocytoma expressed by RT-PCR high levels of mRNA for both CHGA and VGF, confirming VGF as a marker of NE differentiation." (PMID 24277232, 2014). "The aim of the present study was to investigate the tumoral chromogranin A (CgA)-derived peptide WE-14 and the potential advantage to combine plasma WE-14 detection with the EM66 assay and the existing current CgA assay for the diagnosis of pheochromocytoma." (PMID 24523932, 2014). "Right: 57-year-old male patient with pheochromocytoma of the left adrenal gland with lymph node, bone and peritoneal metastases (semi-automated MTV segmentation highlighted in red); Image parameters: MTV = 321 ml, TLU = 924.65; chromogranin A = 2,498 ng/ml, normetanephrine in ELISA = 3,117 pg/ml." (PMID 40445313, 2025).
pheochromocytoma (continued). "Left: 75-year-old female patient with pheochromocytoma of the right adrenal gland (semi-automated metabolic tumor volume (MTV) segmentation highlighted in green); Image parameters: MTV = 18 ml, TLU = 24.6; chromogranin A = 295 ng/ml, normetanephrine in ELISA = 343 pg/ml." (PMID 40445313, 2025). "The histological results show sustentacular cells of pheochromocytomas exhibiting immunoreactivity to the S-100 protein, which closely resembles the chief cells of typical adrenal medulla, displaying an immune response to CD56, chromogranin A, and synaptophysin." (PMID 39822445, 2024). "Furthermore, pheochromocytoma was ruled out based on normal metanephrine, normetanephrine, and Chromogranin A levels." (PMID 40071053, 2024). "For instance, pheochromocytomas are specific for chromogranin A and CD56, while an adrenocortical origin would be suggested by positive for calretinin, MART-1, and inhibin A. Synaptophysin levels can be elevated in both pheochromocytomas and adrenal cortical tumors." (PMID 39290924, 2024). "Chromogranin A staining for a possible pheochromocytoma was performed but was negative." (PMID 35733637, 2022).
neuroendocrine carcinoma (35 papers, 2007 to 2026). A malignant neuroendocrine neoplasm composed of cells containing secretory granules that stain positive for NSE and chromogranin. "In two of the cases with neuroendocrine carcinomas, the dosage of chromogranin A showed that an increase in CgA values was suggestive and was associated with the imaging appearance of metastases." (PMID 39941198, 2025). "CD56, chromogranin A, and synaptophysin are sensitive and specific markers for neuroendocrine cancers." (PMID 38974403, 2024). "All of the patients were diagnosed as neuroendocrine carcinoma according to the immunohistochemical staining (IHC) of specific markers, including chromogranin A (CgA), synaptophysin (Syn), CD56, and Thyroid transcription factor-1 (TTF-1)." (PMID 37920164, 2023). "The overexpression CHGA, a neuroendocrine carcinomas marker, characterizes 10% of infiltrative breast cancer." (PMID 31874600, 2019). "In thymic squamous cell carcinoma, positivity for biomarkers of neuroendocrine carcinoma, such as synaptophysin, neuron-specific enolase, chromogranin A and CD57, has been previously documented." (PMID 25146529, 2015). "Immunohistochemical examination revealed the concurrence of histologically proved neuroendocrine carcinoma (chromogranin A, synaptophysin, and CD56 were positive) and Stage II (T3, N0, and M0) according to the TNM staging classification of colorectal cancer." (PMID 24368955, 2013). "Chromogranin A is therefore considered the most useful marker to confirm neuroendocrine tumors including neuroendocrine carcinoma and carcinoids." (PMID 29147250, 2011). "The lymph node metastases stained diffusely and strongly positive for synaptophysin and chromogranin A, consistent with the light microscopic classification of these as neuroendocrine carcinoma exclusively." (PMID 17988399, 2007). "Expression of chromogranin A, synaptophysin, and various other proteins involved in the formation of neurosecretory granules or CD 56, a neural cell adhesion molecule, can be used as markers of neuroendocrine differentiation, as in neuroendocrine carcinomas of other organs." (PMID 21436947, 2010). "Immunohistochemistry showed positive staining for synaptophysin (Syn), chromogranin A (CgA), CD56, and CK19, which are characteristics of neuroendocrine carcinoma." (PMID 36017024, 2022). "Some institutions use peripheral blood measurements of chromogranin A (CgA) and neuron specific enolase (NSE) as these have been shown to be elevated in some patients with high grade neuroendocrine carcinoma including SCLC and some LCNEC patients." (PMID 34513663, 2021). "Neuroendocrine carcinoma (NEC) is a high‐grade neoplasm with pathological neuroendocrine features, such as expression of chromogranin A and synaptophysin." (PMID 31794158, 2020). "In the case of neuroendocrine carcinomas (WHO, G3), surveillance is performed every 4–6 months in the first year and yearly thereafter (by CT, colonoscopy, and chromogranin A)." (PMID 27525153, 2016). "Notably, neuroendocrine cancer-related markers were significantly upregulated after SCLC transformation, such as SYP, CHGA, INSM1, etc.." (PMID 40437627, 2025). "Neuroendocrine cancer is immunohistochemically negative for AR and positive for chromogranin A, NSE, synaptophysin, CD56 and other markers." (PMID 38305451, 2024). "Additionally, the neuroendocrine chromogranin A and synaptophysin markers were diffusely expressed in C1022 primary tumor and PDX, supporting the diagnosis of poorly differentiated neuroendocrine carcinoma." (PMID 37305585, 2023).
neuroendocrine carcinoma (continued). "The histology showed gallbladder adenocarcinoma, with a single focus of neuroendocrine carcinoma (NEC) component of less than 30%; Ki-67 index > 80%, synaptophysin (Syn) (+), chromogranin A (CgA) (+), and clusters of differentiation (CD) 56 (+) (T2bN1M0, Stage IIIB)." (PMID 34767241, 2022). "Additionally, the expression levels of the neuroendocrine carcinoma markers synaptophysin (SYP) and chromogranin A (CGA) were concordant with those in the original tissue." (PMID 32092044, 2020). "Chromogranin A is another MC product that can be used as a fairly specific marker for MC activation in the absence of cardiac and renal failure, neuroendocrine cancer, and proton pump inhibitor use." (PMID 25909362, 2015). "Focal or aberrant staining for synaptophysin, chromogranin A, CD56 or INSM1 may occur in otherwise conventional gynecologic carcinomas, whereas true poorly differentiated neuroendocrine carcinomas represent aggressive tumors with distinct prognostic and therapeutic implications." (PMID 42196939, 2026). "Neuroendocrine carcinoma are high-grade malignant neoplasms with cells that express little or no chromogranin A, somatostatin receptors, or hormones; however, high expression of INSM1 and synaptophysin has been observed in neuroendocrine carcinoma." (PMID 40491286, 2026). "Last but not least, serum biomarkers such as chromogranin A and neuron‐specific enolase (NSE) should be included in follow‐up of neuroendocrine carcinoma patients." (PMID 39740082, 2025). "Pathology revealed a neuroendocrine carcinoma (NEC) that was positive for synaptophysin and CEA, with a Ki-67 index of 30%, and negative for chromogranin A and CD56." (PMID 39262550, 2024).
neuroblastoma (22 papers, 2003 to 2025). Neuroblastoma (NB) is the most common solid, extracranial childhood tumor. "The TMA also included information on tumor grade, cluster of differentiation 56 (CD56) staining, and chromogranin A (CgA), which are diagnostic markers for neuroblastoma." (PMID 36185250, 2022). "The NB5 assay uses RT-PCR to detect the co-expression of five mRNAs from the neuroblastoma-associated genes, CHGA, DCX, DDC, PHOX2B, and TH." (PMID 34055604, 2021). "In particular, we observed a significant increase of Chromogranin A (CgA) mRNA expression levels, a neuroendocrine secretory protein, which is a useful prognostic and diagnostic tool for neuroblastoma and correlates with tumor burden and survival patients’." (PMID 29930753, 2018). "In clinical neuroblastoma chromogranin A immunoreactivity is associated with tumor hypoxia, but with less dynamic range than IGF2 expression." (PMID 20862257, 2010). "Interestingly, serum chromogranin A levels in patients with neuroblastoma are associated with a worse outcome and patients with advanced disease stages have higher serum levels than those with localized disease." (PMID 38069002, 2023). "Chromogranin A, a protein widely expressed in neuroblastomas that has a strong correlation with cell proliferation, showed a significantly stronger expression in tumors from hyponatremic mice (p ≤ 0.002 vs. control group)." (PMID 38069002, 2023). "At tumor resection following induction chemotherapy, tumor cells stained positive for chromogranin A and synaptophysin and focal ganglion cells, suggestive of neuroblastoma." (PMID 37664065, 2023). "These 3D spheroids retain expression of neuroblastoma markers chromogranin A, synaptophysin and tyrosine hydroxylase and retain their tumorigenic and spontaneous metastatic capacity upon orthotopic injection." (PMID 28924803, 2018). "Recently, Neuro-Endocrine Secretory Protein 55 (NESP55), a novel member of the chromogranin family, was found to be co-expressed with chromogranin A in neuroblastoma." (PMID 20862257, 2010). "We observed that N1E-115 cells express both HIF1α and HIF2α, their common target genes VEGF and adrenomedullin as well as several neuroblastoma classical markers including neuropilin-1, neuronal-specific enolase, Id2 and chromogranin A." (PMID 17655754, 2007). "The neuroblastoma invaded the cranium, compressing the forebrain, and was positive for chromogranin A immunohistochemical staining." (PMID 16507461, 2006). "Chromogranin A labelling was detected in 14 out of 14 neuroblastomas." (PMID 12771991, 2003). "To confirm that the changes in gene expression observed in neuroblastoma cells treated with STM2457 were due to targeting METTL3, we analyzed CHGA and NTRK1 mRNA levels in control SK-N-BE2 cells and cells engineered to overexpress METTL3." (PMID 38691450, 2024). "Increased expression of CHGA, GATA2, and TBX2 was observed with STM2457 treatment in the neuroblastoma xenografts." (PMID 38691450, 2024). "The combined signature of five markers (CHGA, DCX, DDC, PHOX2B, and TH) expression in BM and PB was correlated with PFS of relapsed/refractory neuroblastoma." (PMID 31214500, 2019). "In our previous characterization of the hypoxic phenotype in neuroblastoma we employed two markers, IGF2 and chromogranin A." (PMID 20862257, 2010). "Significant expression of (nor-)adrenergic (“NOR”) markers (i.e., CHGA, CHGB, DBH, TH, PHOX2A, and PHOX2B) is common for healthy sympatho-adrenal cells and tumor NOR populations identified in low-risk neuroblastoma cases (FDR < 0.01, Welch’s t-test)." (PMID 34493726, 2021). "However, in a study of predictive factors for relapse after treatment in 108 bone marrow preparations from 36 children with stage IV neuroblastoma, the degree of Bn immunoreactivity was not significant, whereas chromogranin A and NPY expressions were highly predictive of an unfavorable response." (PMID 34539578, 2021).
neuroblastoma (continued). "Whereas lymphoma, rhabdomyosarcoma, small cell carcinoma, desmoplastic small round cell tumor and neuroblastoma were excluded by negative staining for cytokeratin, CD20, CD3, desmin, myogenin, synaptophysin and chromogranin A." (PMID 40950824, 2025). "Histologically, the primary tumor biopsy did not express common neuroblastoma markers (negative for PHOX2B and TH, but positive for Chromogranin A)." (PMID 37664065, 2023). "Blastemal type WTs and neuroblastomas are both positive for CD56, but WT1 is negative in neuroblastoma, while synaptophysin, chromogranin A, NB84, and PHOX2B are positive in neuroblastoma." (PMID 32204536, 2020).
paraganglioma (22 papers, 2007 to 2025). A benign or malignant neoplasm arising from paraganglia located along the sympathetic or parasympathetic nerves. "Immunohistochemistry confirmed the tumor's chromaffin nature, with chief cells testing positive for CD56, Synaptophysin, and Chromogranin A, and sustentacular cells positive for S100 protein, consistent with a diagnosis of paraganglioma." (PMID 40197392, 2025). "In the second case, the immunohistochemical analysis of the aortic and carotid body paragangliomas revealed multifocal mild to moderate positivity for Chromogranin-A (Cr-A), with neoplastic cells exhibiting granular brown cytoplasmic staining." (PMID 39591360, 2024). "Paragangliomas co-express vimentin, chromogranin A and synaptophysin but lack cytokeratins and calcitonin." (PMID 35805976, 2022). "In HNPGLs, Chromogranin A correctly predicts the result of paraganglioma surveillance more often in patients with SDHB compared with those with SDHD (77% vs. 22%, p = 0.003) and has less added benefit to standard surveillance." (PMID 35054195, 2021). "Apart from central necrosis, vascular and lymphatic invasion and mitotic abnormalities; chromogranin A, vimentin, S-100, synaptophysin can be used in the immunohistochemical analysis of paragangliomas and indicate the true nature of the tumour." (PMID 29255564, 2017). "The resected tumor was diagnosed as the ACTH-secreting paraganglioma in the pathological examination, which was confirmed by immunohistochemical studies with chromogranin A, synaptophysin, and ACTH." (PMID 28225994, 2017). "Immunohistochemical staining was positive for synaptophysin and chromogranin A. Based on these findings, the resected tumors were histopathologically diagnosed with liver metastases from the retroperitoneal paraganglioma." (PMID 26943413, 2015). "Paraganglioma and pheochromoctyoma were also reported to cause hyperinsulinemic hypoglycemia and also show tracer uptake by SRS and are immunoreactive for chromogranin A and syanptophysin." (PMID 24741994, 2014). "After successful resection of the intrapericardial mass, which was histologically shown to be a chromogranin A-positive paraganglioma, the patient was discharged normotensive." (PMID 24688789, 2014). "Chromogranin A and synaptophysin are the most common neuropeptides synthesized in endocrine cells and can be used for immunohistochemical analysis of paragangliomas along with other protein markers such as neuron specific enolase and vimentin." (PMID 23537060, 2013). "Paragangliomas stain substantially positive for chromogranin A and synaptophysin and exclusively positive for S-100 proteins, while gastrointestinal glomus tumors barely stain positive for S-100 proteins." (PMID 23691399, 2013). "The differential diagnosis between parathyroid and thyroid tumours, paraganglioma, haematological or metastatic tumours can be clarified via PTH, chromogranin A, TTF-1, calcitonin, LCA, CD56 and vimentin, among others." (PMID 35805976, 2022). "Furthermore, Chromogranin A does not provide an additive benefit to standard surveillance for predicting the presence of SDHB- or SDHD-related paraganglioma but has a useful negative predictive value when normal in patients with an SDHB mutation." (PMID 34072806, 2021). "Paraganglioma, but not ASPS, expresses neuroendocrine markers, such as chromogranin A and synaptophysin." (PMID 26369552, 2015). "GIST and paraganglioma appeared to be ruled out because the tumor was CD117-, DOG-1-, S100-, and chromogranin A-negative." (PMID 26187280, 2015). "In our case, the tumor cells were HMB-45 negative combined with positivity for chromogranin A and CD56, thus favoring paraganglioma rather than malignant melanoma." (PMID 22741527, 2012).